WDR25 (WD repeat domain 25)
Synonyms: C14orf67; MGC4645
Tractability: PROTAC: ubiquitination databases record sites on it.
Gene: Protein-coding gene on chromosome 14 (100,376,418 to 100,530,306, forward strand). Ensembl gene ENSG00000176473.
Subcellular location (Human Protein Atlas): Nucleoplasm; Predicted to be secreted
Gene Ontology:
Molecular function: protein binding
Genetic constraint (gnomAD): Loss-of-function variants: 32 observed, 45.57 expected, observed/expected ratio (o/e) 0.7, 90% interval 0.53 to 0.94. The upper end of that interval is the gene's LOEUF score, 0.94, which puts it in group 4 of 6, group 1 being the genes least tolerant of losing a copy. Missense variants: 568 observed, 650.09 expected, observed/expected ratio (o/e) 0.87, 90% interval 0.81 to 0.94. Synonymous variants: 219 observed, 255.69 expected, observed/expected ratio (o/e) 0.86, 90% interval 0.77 to 0.96.
Homologues: Orthologues: chimpanzee WDR25 (99% identical), macaque WDR25 (94% identical), dog WDR25 (80% identical), mouse Wdr25 (78% identical), rat Wdr25 (76% identical), pig WDR25 (76% identical), guinea pig WDR25 (55% identical), tropical clawed frog wdr25 (41% identical). Paralogues in human: CDC40 (21% identical), WDR87 (17% identical).
Diseases named in the same sentence as WDR25 in open-access papers:
WDR25 is named in the same sentence as 4 diseases in open-access papers, as found by Europe PMC text mining. Sharing a sentence is not in itself a finding about the gene and the disease.
WDR25 shares sentences with these, for which no sentence is quoted: asthma (1 paper); cardiovascular disease (1); Obesity (1); type 2 diabetes (1).